INPP4B (inositol polyphosphate-4-phosphatase type II B)
Diseases named in the same sentence as INPP4B in open-access papers (continued):
Sharing a sentence is not in itself a finding about the gene and the disease.
prostate carcinoma (31 papers, 2011 to 2026). A carcinoma that arises from epithelial cells of the prostate gland. "We showed that INPP4B knockdown causes a decrease in EZH2 levels in two independent prostate cancer cell lines, LNCaP and VCaP." (PMID 38001678, 2023). "We describe common and distinct compensatory changes caused by the loss of INPP4B in human cell lines, mouse prostate, and normal human prostate epithelium and prostate cancers." (PMID 38001678, 2023). "Immunostaining to detect INPP4B in prostate carcinoma clinical samples has also identified INPP4B loss as an independent prognostic marker, correlating with reduced biochemical (PSA) relapse-free survival." (PMID 32630372, 2020). "Loss of INPP4B expression in prostate cancers is associated with reduced time for biochemical recurrence and poorer outcomes." (PMID 28082369, 2017). "We and others have previously shown that loss of INPP4B expression correlates with poor prognosis in multiple malignancies and with metastatic spread in prostate cancer." (PMID 25248616, 2014). "Inositol polyphosphate 4-phosphatase type II (INPP4B), is a tumor suppressor gene implicated in many cancers including: breast, ovarian and prostate cancers." (PMID 24931005, 2014). "Of note, patients with decreased INPP4B levels in their prostate cancer tissues had significantly increased risk of biochemical recurrence." (PMID 21487159, 2011). "Similarly, in prostate cancer, loss of INPP4B correlates with poor prognosis and reduced time to biochemical recurrence by promoting AKT activation." (PMID 32296634, 2020). "Our data cautions that androgen ablating therapies might promote loss of INPP4B, which in turn could facilitate prostate cancer growth and metastasis through activation of Akt and PKC signaling." (PMID 25248616, 2014). "Thus, loss of INPP4B in prostate cancers may cause increased IL-8 expression, activation of AR, and changes in the tumor microenvironment that lead to prostate cancer progression." (PMID 25248616, 2014). "Therefore, loss of INPP4B during prostate cancer progression may cause stimulation of multiple oncogenic signaling pathways, which facilitate tumor cell invasion and metastatic spread." (PMID 25248616, 2014). "INPP4B inactivation in primary prostate cancers and preneoplastic lesions promotes the transition from androgen-regulated differentiation to proliferation." (PMID 41363115, 2025). "Since EZH2 acts as an oncogene in prostate cancer, we correlated INPP4B and EZH2 expression in indolent and aggressive human prostate cancers." (PMID 38001678, 2023). "It has been demonstrated that overexpression of INPP4B induces chemosensitivity in human hepatocellular carcinoma and prostate cancer cells lines." (PMID 36993823, 2023). "This was confirmed in another study which documented how INPP4B impacts the AR transcriptional program and that its depletion stimulates prostate cancer cell proliferation." (PMID 36768610, 2023). "Knockdown of INPP4B reduces the EZH2 in prostate cancer cell lines on both the RNA and protein levels." (PMID 38001678, 2023). "Similar to PtenloxP/loxP; PB4-Cre, the deletion of Inpp4b alone is insufficient for the development of invasive prostate cancer, despite increased phosphorylation levels of Akt and increased prostate inflammation." (PMID 38001678, 2023). "For example, in prostate cancer, the expression of INPP4B is regulated by androgens, which promote its expression in human prostate cells." (PMID 36147923, 2022). "INPP4B suppresses cell invasiveness in prostate cancer and hepatocellular carcinoma but promotes colorectal cancer cell proliferation." (PMID 36147923, 2022). "Chen and colleagues probed the PI3K/AKT pathway using the tumor suppressor inositol polyphosphate 4-phosphatase B (INPP4B) on prostate cancer cells, finding that overexpression of INPP4B led to increased sensitivity to docetaxel." (PMID 33672595, 2021).
prostate carcinoma (continued). "Overexpression of INPP4B in prostate cancer cells results in suppressed migration, invasion and angiogenesis." (PMID 34729121, 2021). "In colon cancer cells, INPP4B acts as an oncogenic factor that positively regultates AKT 26411369, whereas INPP4B suppresses cancer progression in prostate cancer cells by reducing tumor migration, invasion, and angiogenesis." (PMID 34977872, 2021). "INPP4B is emerging as a tumour suppressor in various types of cancers including prostate cancer, ovary cancer, and triple-negative breast cancer." (PMID 26573229, 2015). "Among the 6 candidate transformation suppressors, INPP4B is a known tumor suppressor involving in breast and prostate cancer, the roles of the rest candidate genes in suppression of cell transformation have not been clear or well- characterized yet." (PMID 25962159, 2015). "Recent studies have proved evidence about INPP4B in several human cancers, including prostate cancer, melanoma, and breast cancer." (PMID 25542038, 2014). "In contrast, inhibition of PKC signaling phenocopied INPP4B-mediated inhibitory effect on IL-8 in either prostate cancer cell line." (PMID 25248616, 2014). "Loss of INPP4B and increased COX-2 and serum IL-8 levels with prostate cancer progression were previously reported." (PMID 25248616, 2014). "These genes were regulated in a reciprocal manner following downregulation of INPP4B in the independently derived INPP4B-positive LNCaP prostate cancer cell line." (PMID 25248616, 2014). "We demonstrate that de novo expression of INPP4B in highly invasive human prostate carcinoma PC-3 cells suppresses their invasion both in vitro and in vivo." (PMID 25248616, 2014). "Levels of INPP4B are found to be induced by the androgen receptor in prostate cancer cells and play an important role in androgen-ablation therapy of prostate cancers." (PMID 22121480, 2012). "The INPP4B expression levels should be taken in consideration when Androgen-ablation therapies are utilized for patients with advanced prostate cancers." (PMID 22121480, 2012). "To date, androgen driven regulation of INPP4B expression in human prostate cancer cell lines is the only known upstream regulator of INPP4B gene and protein expression." (PMID 21487159, 2011). "Using immunohistochemistry we have shown highly significant downregulation of INPP4B protein in prostate cancers relative to benign prostate epithelium in radical prostatectomy specimens from men with clinically localized prostate cancer." (PMID 21487159, 2011). "We have previously reported that INPP4B is a tumor suppressor in human prostate cancer." (PMID 38001678, 2023). "Since LNCaP cells do not express PTEN, we used the prostate cancer cell line, VcaP, to compare the effects of INPP4B and PTEN loss on EZH2 protein levels." (PMID 38001678, 2023). "Among the most frequently deleted tumor suppressors in prostate cancer are INPP4B and PTEN." (PMID 38001678, 2023). "Knockdown of INPP4B but not PTEN in human prostate cancer cell lines caused a decrease in EZH2 expression." (PMID 38001678, 2023). "Only the loss of INPP4B in HFD-fed mice promoted prostate neoplasia, suggesting that INPP4B might provide a functional link between obesity and increased prostate cancer incidence." (PMID 33772116, 2021). "The low expression of INPP4B in mouse prostate was also confirmed by RNA sequencing (RNA-seq) (C. Sandi, personal communication), and it is consistent with similar rates of prostate cancer development in PTEN single-KO and PTEN-INPP4B double-KO mice (data not shown)." (PMID 29056325, 2017). "In addition, examination of INPP4B function in prostate cancer has supported its role as a tumour suppressor." (PMID 28082369, 2017). "INPP4B knockdown promotes AKT-mediated prostate cancer cell growth and proliferation." (PMID 28082369, 2017).
prostate carcinoma (continued). "To test whether INPPB4 expression is androgen-dependent, we used human prostate cancer xenografts derived from the androgen-responsive, INPP4B-positive xenograft line LTL-418, originally obtained from a high-grade prostate adenocarcinoma." (PMID 25248616, 2014). "INPP4B is induced by androgens in multiple androgen-sensitive human prostate cancer cell lines." (PMID 25248616, 2014). "Therefore, our findings apparently exclude impaired matrix proteolysis from the inhibitory effects of INPP4B overexpression on invasion of prostate cancer cells." (PMID 25248616, 2014). "These in vivo data confirmed our in vitro findings that INPP4B suppresses prostate cancer invasion." (PMID 25248616, 2014). "In our previous report, we demonstrated that AR directly regulates expression of INPP4B in prostate cancer cells, suggesting that castration may lead to a decline in INPP4B and activation of Akt signaling." (PMID 25248616, 2014). "INPP4B was recently demonstrated to have reduced expression in cancer cells and was identified as a tumor suppressor in breast and prostate cancers, yet its role in BCa remains unclear." (PMID 25277204, 2014). "We have shown that INPP4B is directly regulated by AR in LNCaP and VCaP prostate cancer cells." (PMID 21487159, 2011). "Thus, based on both clinical and biological evidence INPP4B appears to be a tumor suppressor gene in prostate cancer and is inactivated at rates similar to the classic tumor suppressor gene PTEN." (PMID 21487159, 2011). "Although AR induction of INPP4B has been demonstrated for androgen-dependent human prostate cancer cell lines, it has remained unclear whether INPP4B would decline in clinically-derived human prostate cancer tissue during castration." (PMID 25248616, 2014). "For INPP4B, loss of expression or mutations were found in 8% and 47% of primary tumors and metastases respectively, while for PTEN similar changes were found in 4% of primary tumors and 42% of metastases suggesting a tumor suppressor role for INPP4B in prostate cancer." (PMID 21487159, 2011). "Reduced INPP4B levels are seen in prostate cancer, and overexpression leads to the inactivation of the PI3K/AKT/mTOR pathway and suppression of prostate cancer cell migration and invasion." (PMID 36768610, 2023). "In men, there is a positive correlation between the expression of INPP4B and EZH2 in primary prostate cancers." (PMID 38001678, 2023). "INPP5D deep deletion is observed in as many as 3.8% of patients with prostate cancer whereas INPPL1 and INPP4B are amplified in up to 2.9% of cases." (PMID 32630372, 2020). "INPP4B shRNA knockdown in LNCaP prostate cancer cell lines increased cell proliferation and AKT activation, whereas its ectopic expression in PC-3 prostate cancer cells decreased in vivo stromal invasion in chick–embryo models." (PMID 28082369, 2017). "To elucidate metastasis signaling pathways regulated by INPP4B, we used PC-3 cells, an invasive prostate cancer cell line that expresses very low endogenous levels of both PTEN and INPP4B." (PMID 25248616, 2014). "A similar effect of INPP4B depletion on the PI3K/AKT signaling axis was previously demonstrated in melanoma, breast and prostate cancers." (PMID 25126743, 2014). "PC-3 is an invasive human prostate cancer cell line that has the lowest levels of PTEN and INPP4B expression in the tested panel of six prostate cancer cell lines." (PMID 25248616, 2014). "We evaluated castration sensitivity of INPP4B in the androgen-dependent human prostate cancer LTL-418 xenograft and found that INPP4B expression was significantly reduced following castration." (PMID 25248616, 2014). "INPP4B and PTEN dual specificity phosphatases are frequently lost during progression of prostate cancer to metastatic disease." (PMID 25248616, 2014). "Both INPP4B and PTEN are tumor suppressors in prostate cancer." (PMID 38001678, 2023).
prostate carcinoma (continued). "Furthermore, INPP4B depletion significantly increased proliferation of the PTEN negative prostate cancer cell line LNCaP." (PMID 21487159, 2011). "Interestingly, PTEN/INPP4B loss in non-transformed cells (Mcf10a) potentiates EGF-dependent AKT phosphorylation and invadopodia formation, although it has opposite effects in breast and prostate cancer cells, reducing AKT activation possibly by inhibiting class I PI3K signaling." (PMID 32296634, 2020). "Evaluation of the gene expression data in 499 prostate cancer patients in the TCGA dataset showed that EZH2 expression positively correlates with INPP4B (r = 0.1368, p = 0.0022), while the correlation is negative with PTEN expression (Spearman r = −0.1718, p = 0.0001)." (PMID 38001678, 2023).
melanoma (22 papers, 2014 to 2024). A malignant, usually aggressive tumor composed of atypical, neoplastic melanocytes. "The association of INPP4B with survival was in-line with previously reported tumor suppressive function in bladder cancer, and putative tumor-promoting role in melanoma and AML." (PMID 29415082, 2018). "Loss of INPP4B expression has been found in various human cancers with major loss in breast, ovarian and prostate cancers, as well as in melanomas and results in increased cell proliferation, migration and invasion." (PMID 25868852, 2015). "Upregulation of INPP4B in melanoma cells was associated with loss of miRNA (miR)-494 and/or miR-599 due to gene copy number reduction." (PMID 26573229, 2015). "Further along this line, loss of INPP4B significantly inhibited proliferation of NPM1-mutated OCI-AML3 cells, and overexpression of INPP4B enhanced proliferation of melanoma cells and melanocytes as well as colon cancer cells, in which INPP4B acts as an oncogenic driver." (PMID 36993823, 2023). "On the other hand, genomic loss of miR-494 or miR-599 promotes increased INPP4B expression in melanoma cells, and introduction of antisense-miRNA oligonucleotides targeted to miR494 or miR599 promotes melanoma cell proliferation through up-regulation of INPP4B." (PMID 28082369, 2017). "Indeed, high INPP4B protein expression in fresh melanoma isolates and melanoma cell lines was associated with high pSGK3T320 levels." (PMID 28082369, 2017). "Therefore, upregulation of INPP4B through loss of miR-494 and miR-599 is highly selective in melanoma cells." (PMID 26573229, 2015). "Moreover, we show that the increase in INPP4B in melanoma is due to loss of microRNA-494 (miR-494) and/or miR-599 as a result of copy number reduction of chromosome segments where they are respectively located." (PMID 26573229, 2015). "However, whether elevated INPP4B is associated with resistance to treatment and poor patient outcome in melanoma as is it in AML remains to be clarified." (PMID 26573229, 2015). "Increased INPP4B expression was likewise reported in acute myeloid leukemia, colon cancer, and some melanoma subtypes supporting the notion of INPP4B as an oncogene." (PMID 36993823, 2023). "Adenylate cyclase type 3 (Adcy3) and inositol polyphosphate 4‐phosphatase type II (Inpp4b) were identified as genes regulated by DNA methylation that, respectively, affect melanoma growth and metastasis." (PMID 35075772, 2022). "The authors found that overexpression of sd/miR-605 decreases cellular INPP4B, leading them to conclude that sd/miR-605 suppresses melanoma growth through the inhibition of INPP4B." (PMID 36009366, 2022). "We evaluated metastatic formation in mouse lungs, a common site for melanoma metastases, by intravenously injecting 4C11+ cells silenced for Adcy3, Inpp4b, or control cells." (PMID 35075772, 2022). "In order to better understand the epigenetic regulation of Lrrk2, Inpp4b, and Adcy3 in our murine melanoma model, we analyzed the ERBBS and expression data for CpG resolution methylation levels." (PMID 35075772, 2022). "Inpp4b was described as a melanoma tumor suppressor via AKT regulation and an oncogene based on its role in activating SGK3." (PMID 35075772, 2022). "Copy number reduction of PTEN, INPP5J and INPP4B have been reported to be relatively common in melanoma." (PMID 33549048, 2021). "Paradoxically, more recent studies have indicated a possible oncogenic role for INPP4B in acute myeloid leukemia (AML) associated with chemoresistance, as well as in melanoma and colon cancer." (PMID 34035258, 2021). "Studies in breast, prostate, melanoma and ovarian cancers provided evidence for the tumor suppressive role of INPP4B." (PMID 29415082, 2018). "Another report recently showed evidence that miR-605-5p acts as a tumor suppressor in melanoma by inhibiting INPP4B." (PMID 29603092, 2018).